Y_RNA (Y RNA )
Gene: Miscellaneous RNA gene on chromosome 2 (85,332,895 to 85,332,996, reverse strand). Ensembl gene ENSG00000239143.
Homologues: Orthologues: macaque Y_RNA (94% identical), guinea pig Y_RNA (75% identical). Paralogues in human: RNY4 (77% identical), RNY4P3 (77% identical), RNY4P36 (77% identical), RNY4P6 (77% identical), Y_RNA (77% identical), RNY4P7 (76% identical), Y_RNA (76% identical), RNY4P14 (75% identical), Y_RNA (75% identical), RNY4P10 (75% identical), RNY4P17 (75% identical), RNY4P34 (75% identical), and 88 more.